TRAV19 (T cell receptor alpha variable 19)
Description:
V region of the variable domain of T cell receptor (TR) alpha chain that participates in the antigen recognition. Alpha-beta T cell receptors are antigen specific receptors which are essential to the immune response and are present on the cell surface of T lymphocytes. Recognize peptide-major histocompatibility (MH) (pMH) complexes that are displayed by antigen presenting cells (APC), a prerequisite for efficient T cell adaptive immunity against pathogens. Binding of alpha-beta TR to pMH complex initiates TR-CD3 clustering on the cell surface and intracellular activation of LCK that phosphorylates the ITAM motifs of CD3G, CD3D, CD3E and CD247 enabling the recruitment of ZAP70. In turn ZAP70 phosphorylates LAT, which recruits numerous signaling molecules to form the LAT signalosome. The LAT signalosome propagates signal branching to three major signaling pathways, the calcium, the mitogen-activated protein kinase (MAPK) kinase and the nuclear factor NF-kappa-B (NF-kB) pathways, leading to the mobilization of transcription factors that are critical for gene expression and essential for T cell growth and differentiation. The T cell repertoire is generated in the thymus, by V-(D)-J rearrangement. This repertoire is then shaped by intrathymic selection events to generate a peripheral T cell pool of self-MH restricted, non-autoaggressive T cells. Post-thymic interaction of alpha-beta TR with the pMH complexes shapes TR structural and functional avidity.
Synonyms: TCRAV12S1; TCRAV19S1
Gene: T-cell receptor variable (V) gene on chromosome 14 (22,007,512 to 22,008,181, forward strand). Ensembl gene ENSG00000211799.
Subcellular location: Cell membrane
Pathways (Reactome):
Immune System: Co-inhibition by PD-1; Downstream TCR signaling; Generation of second messenger molecules; Immunoregulatory interactions between a Lymphoid and a non-Lymphoid cell; Phosphorylation of CD3 and TCR zeta chains; Translocation of ZAP-70 to Immunological synapse
Gene Ontology:
Molecular function: MHC protein binding; peptide antigen binding
Biological process: immune response
Cellular component: immunoglobulin complex; plasma membrane
Homologues: Orthologues: macaque TRAV19 (93% identical), rabbit TRAV19 (68% identical), mouse Trav16n (64% identical), mouse Trav16 (63% identical), mouse Trav16d-dv11 (62% identical). Paralogues in human: TRAV14DV4 (56% identical), TRDV1 (55% identical), TRAV9-1 (28% identical), TRAV9-2 (28% identical), IGLV5-37 (28% identical), TRAV18 (28% identical), TRDV3 (28% identical), IGKV6D-41 (27% identical), IGLV1-40 (27% identical), IGLV11-55 (27% identical), IGLV5-45 (27% identical), TRAV40 (27% identical), and 81 more.
Diseases named in the same sentence as TRAV19 in open-access papers:
TRAV19 is named in the same sentence as 3 diseases in open-access papers, as found by Europe PMC text mining. Sharing a sentence is not in itself a finding about the gene and the disease. The quoted sentences say what the papers report.
acute lymphoblastic leukemia (1 paper, 2022). Leukemia with an acute onset, characterized by the presence of lymphoblasts in the bone marrow and the peripheral blood. "T cells transduced with the JDI TCR, encoded by TRAV19*01 and TRBV6-2*01, were co-cultured with peptide-pulsed HLA-A*11+ acute lymphoblastic leukemia SUP-B15 B cells." (PMID 36088370, 2022).
melanoma (1 paper, 2018). A malignant, usually aggressive tumor composed of atypical, neoplastic melanocytes. "Indeed, we reported before that MELOE-1 specific T cell repertoire was also a vast T cell repertoire in HLA-A2 healthy donors and melanoma patients, and that MELOE-1 specific T cells were strongly biased toward TRAV19 usage." (PMID 30214446, 2018).
infection (1 paper, 2024). The state of being infected such as from the introduction of a foreign agent such as serum, vaccine, antigenic substance or organism. "The DEG analysis showed that LAIR2, CD7, KLRB1, TYROBP, TRAV19, TRAV21, and TRBV6-5 were upregulated in group E VS group B both breakthrough infection by BA.5.2." (PMID 39835127, 2024).